CD34 (CD34 molecule)
Diseases named in the same sentence as CD34 in open-access papers (continued):
Sharing a sentence is not in itself a finding about the gene and the disease.
tumor (continued). "One of four tumors was positive for c-kit and CD34 expression, with a mitotic index of 3/50 high-power fields; this tumor was ultimately diagnosed as GIST of the esophagus, with a low risk of aggressive behavior." (PMID 25889037, 2015). "Surprisingly, CD34+/Itga6high and CD34−/Itga6high tumour cells display similar tumour growth rates and sizes." (PMID 25608467, 2015). "On immunohistochemistry assay the tumor cells stained uniformly for stem cell factor CD34 and c-kit (CD-117), variably positive for SMA and S-100, and negative for desmin." (PMID 25717425, 2015). "In the present study, CD34 and factor VIII-associated antigen immunopositive tumour cells were detected, indicating the presence of EHE." (PMID 25663869, 2015). "What is more important, immunohistochemical analysis of xenograft tumor sections for endothelial markers, including VWF and CD34, revealed that tumor angiogenesis was less in HT-29 CASP3DN cell xenograft than in parental HT-29 cell xenograft." (PMID 26431328, 2015). "This would account for the existence of tumor markers CD34 and CD56 in both DFSPs and vascular leiomyomas." (PMID 25924890, 2015). "The endothelial FSHR expression correlated significantly with the peritumoral CD34+ vessels’ density (p < 0.001) and tumor size (p = 0.01)." (PMID 25652007, 2015). "The MVD in tumor tissues is determined by evaluating tumor-derived vascular endothelial cells using monoclonal antibodies, including CD-31, CD-34 and FactorVIII." (PMID 25955495, 2015). "The endothelial marker CD34 was shown to be positive in two of the NF1 tumor models (including the corresponding primary tumors) but negative for the rest of cases." (PMID 25810463, 2015). "Of WAT-derived cells, CD34+ cells seem to be at least partly responsible for tumor-promoting ability, as they increased tumor sizes significantly when coinjected with BCCs." (PMID 26000019, 2015). "When CD34− tumor cells from Ki20227 treated animals were analyzed there was a significant reduction in Sms expression, but a further increase in APAO expression." (PMID 25762633, 2015). "Further, CD34 stained mean-vessel-area in tumor is positively correlated with tumor-to-normal total-hemoglobin and oxy-hemoglobin concentration." (PMID 26013572, 2015). "Intraperitoneal injections of JSI-124 resulted in pronounced decrease in tumor cell proliferation and CD34-positive endothelial cells, and marked reduction expression of p-VEGFR2 and p-STAT3 in solid tumors." (PMID 25789853, 2015). "Note also, tumor blood flow indices defined by these authors correlated positively with the expression of CD34 and CD105 and with the expression of Ki67." (PMID 26013572, 2015). "We thus examined the expression of CD34, a specific endothelial cell marker, in sections from tumor xenografts, and found that there was a clearly increased microvascular density (MVD) in tumors overexpressing OCT4B." (PMID 25816351, 2015). "In the non-tumour control cells (CD34+ HSC and CD133+ HSC), both doxorubicin and etoposide when combined with each of the polyphenols had a minimal effect on caspase 3 activity." (PMID 27551472, 2015). "CD34 highlighted the rich vasculature of the tumor tissue and staining of the sinusoidal endoethelial cells." (PMID 26122043, 2015). "Anti-CD34 immunohistochemical analysis of tumor sections from the S180-xenografted mice revealed that DVDMS-mediated SDT significantly reduced microvessel density (MVD) after treatment." (PMID 26631871, 2015). "We employed a range of antibodies to characterize the immunophenotype of the tumor cells and found that the tumor cells were positive for CD34, CD99, bcl-2, and vimentin." (PMID 25688313, 2015). "DVDMS-SDT, compared with ultrasound therapy alone, resulted in enhanced inhibition of the tumor vasculature indicated by CD34-positive endothelial cells (brown)." (PMID 26631871, 2015).
tumor (continued). "Immunohistochemistry of PACE4 knockdown tumors revealed reduced Ki-67 (proliferation marker), higher p27KIP (quiescence marker) and cleaved PARP (Apoptosis marker) levels along with a decrease in tumor microvascularization, as seen from CD34 immunostaining." (PMID 25682874, 2015). "We next examined expression in orthotopic tumor tissues of the cell proliferation marker, Ki67, and the angiogenesis marker, CD34, by immunohistochemistry." (PMID 25605009, 2015). "CD34 positive blood vessels within a manually edited buffer of 300 μm from any tumor cell in all directions were identified and individually quantified for each sample." (PMID 24755315, 2014). "The adjacent cortex showed labelling of glial cells in layer I and in occasional cortical neurones but the pattern and distribution, in both tumour and peri-tumoral cortex, differed to that observed with CD34 labelling." (PMID 25005575, 2014). "The effect of VPA on tumor angiogenesis was tested in mice transplanted with Kasumi-1 cells by measuring MVD using CD34 immunostaining, which has been used in previous studies." (PMID 24297248, 2014). "At four weeks after major hepatectomy and partial hepatic I/R injury, IHC staining revealed that strong expression of CD34 in intrahepatic metastatic tumor nodules were detected in the control group." (PMID 24766798, 2014). "The CD34-positive cell neoplasm most closely aligned to GCA is the SFT, which was first described in the pleura but has since been reported in many locations." (PMID 24758544, 2014). "Then, immunohistochemical detection of VEGF-A and CD34 expression in mice tumor xenograft was performed." (PMID 25428912, 2014). "PNS treatment led to decreased expression of CD34 and vWF in tumor and increased expression of these vascular markers in heart." (PMID 24903055, 2014). "The histopathological examination revealed CD34 expression in endothelial cells and thin-walled vessels with a concentric, perivascular gathering of spindled myoid tumor cells as similarly described in the literature." (PMID 25349759, 2014). "The rationale for development of the method for immunocapture of AML blast-derived exosomes from plasma of patients with CD34+ AML is based on existing evidence for selective ability of tumor-derived exosomes (TEX) to mediate immunosuppression." (PMID 25093329, 2014). "In the present study, the effects of VPA were directly tested on tumor angiogenesis in mice transplanted with Kasumi-1 cells by measuring the MVD with CD34 immunostaining." (PMID 24297248, 2014). "Immunohistochemistry showed that 79 to 100% of the tumor cells had positive expression for CD34, which was a highly specific marker of SFTs." (PMID 25351104, 2014). "Immunohistochemical analysis showed tumor cells positive for c-kit and CD34, and cerebellar metastasis of GIST was diagnosed." (PMID 25610678, 2014). "TADCs are able to differentiate into endothelial-like cells under tumor specific culture conditions and CD34− CD11c+ immature DCs cocultured with tumor-cell conditioned media showed an endothelial-like differentiation." (PMID 25254213, 2014). "To determine the effect of CXCR4 inhibition on tumor angiogenesis we measured hotspots of angiogenesis in primary and lymph node metastatic tumor tissues for CD34 positive blood vessels." (PMID 24472670, 2014). "Although GCF is composed of CD34 positive spindle and stellate shaped cells including multinucleated floret-like giant cells and tumor cell-lined pseudovascular spaces, it has infiltrative margins and has less conspicuous cellularity and vasculature." (PMID 24758544, 2014). "Otherwise, the micro-vessels displayed by CD34 signaling indicated that the more micro-vessels was necessary for supporting and supplying the bigger xenografts tumor formation." (PMID 25070141, 2014).
tumor (continued). "After complete surgical removal of the tumor, immunohistochemical analysis revealed strong positivity for the mesenchymal markers vimentin, CD34, CD31 and CD99 in neoplastic cells." (PMID 24758544, 2014). "From this we were able to generate heat maps representing the cell surface profile of the hematopoietic (CD45+), vascular endothelial (CD31+/CD34+), fibroblast (TE7+) and cancer (CD45−/CD31−/CD34−/TE7−) cell populations within each tumor." (PMID 25170899, 2014). "HNSCC cells trigger increased IL-6 production from CD34+ progenitor cells, for example, promoting angiogenesis in the tumor microenvironment." (PMID 24698959, 2014). "Our study requires analysis of vascular EC in patient ccRCC through automated analysis of large batches of multi-spectral images of tumor slides immunostained for CD34 to reveal EC (250–500 images/batch are common)." (PMID 24603893, 2014). "The expression density of CD34 was particularly high in tumor-derived ECs, and that of CD54 and CD144 in ECs of repair blastemas." (PMID 24632811, 2014). "Consistently with the result from CD34 expression analysis, a significant decrease in the expression of vWF was observed in the tumor sections of PNS-treated complex mice compared to that from the vehicle-treated complex mice." (PMID 24903055, 2014). "The two groups differed significantly in gender, age, greatest tumor diameter, risk stratification, tumor-associated ulcers, and CD117 and CD34 expression (P <0.05 each)." (PMID 24479763, 2014). "The rich blood supply to the tumor was evident from many blood vessels confirmed on the immunohistochemically stained sections, which showed CD34 positivity in vascular endothelial cells." (PMID 24678877, 2014). "The immunohistochemical analysis showed that the tumor cells reacted with endothelial marker CD34, which is usually expressed by normal and abnormal endothelial cells." (PMID 25184066, 2014). "Immunohistochemical staining for CD34 was used to evaluate the number and morphologic characteristics of blood vessels within each tumor." (PMID 24736504, 2014). "MVD is evaluated in highly vascularized tumor areas (hot spots) by immunohistochemical assays using pan-endothelial antibodies (CD34, CD31 and von Willebrand factor)." (PMID 24507660, 2014). "The in vivo imaging results were correlated with ex vivo IHC staining of CD34 in tumor sections, indicative of the microvascular density." (PMID 25384034, 2014). "Using this model, we demonstrated that the CMP develop into APL by transducing PML-RARA whereas the resultant CD34− APL cells had the ability to maintain the tumor." (PMID 25369030, 2014). "CD34 is a marker for micro-vessels, and the abundant vessels are necessary for supplying the tumor growth." (PMID 25070141, 2014). "With the purpose of understanding differences in growth kinetic among all groups, necrotic areas as well as tumor vessels were evaluated by routine histopathology and using immunohistochemistry with anti-CD34 antibodies." (PMID 24421272, 2014). "Immunohistochemically, the tumor mostly showed diffusely strong CD34, CD99, Bcl-2 and vimentin staining." (PMID 24443842, 2014). "CD34+ blood vessels were typically distributed throughout tumours, in malignant nodules, sheets and septa, or in a minority of cases, concentrated in septa." (PMID 24961933, 2014). "Accordingly, the amount of MVD determined by CD34 immunostaining was lower in the tumor derived from miR-126 restoration group (20.05 ± 3.39) than that from the control group (30.35 ± 3.34) and miR-126 down-regulated group (52.00 ± 4.47)." (PMID 25428912, 2014).
tumor (continued). "Immunohistochemical staining using anti-CD34 antibody on tumor tissues from either treated or untreated nude mice with SD-208 showed cytoplasmic membrane of endothelial cells in brown color and marked microvessels proliferation." (PMID 24902843, 2014). "Tumor sections were immunostained with a primary anti-tryptase antibody and an anti-CD-34 antibody by means of immunohistochemistry." (PMID 25056597, 2014). "Lipoaspirates of white adipose tissue were found to contain CD34+ progentiors that contributed to tumor vascularization." (PMID 24586900, 2014). "Histological assessment on H&E and CD34 revealed low vascularity confined mainly to the tumor rim, which is in agreement with DCE-MRI findings." (PMID 24835641, 2014). "Expression of CD34 was upregulated in the tumor area after concurrent chemoradiotherapy in six of seven patients with less than pathological complete response and zero of two patients with pathological complete response (P = 0.08)." (PMID 25373828, 2014). "This shows that activated M2-like macrophages derived from either tumor-bearing or wild-type mice stimulate sphere formation by CD34− TICs." (PMID 25294815, 2014). "Histopathological examinations revealed that CD34-positive spindle-shaped eosinophilic tumor cells spread from the muscularis propria to the adventitia with marked hyalinization (image not shown)." (PMID 25022862, 2014). "The higher expression of CD31, CD105 and CD34 on ECs from the B16-F0 tumor correlates with the faster tumor growth compared to that of CT26 tumors." (PMID 24632811, 2014). "Tumor angiogenesis was evaluated by CD34-determined intratumoral MVD in the present study, and high MVD was also associated with high HIF-1α expression and high VEGF expression." (PMID 25162518, 2014). "We separated CD8 T cells and CD34 myeloid blasts, rested them overnight and re-exposed T cells to tumor cells from different time points to measure cytotoxic recognition by CD8 T cells." (PMID 24681961, 2014). "Primary tumor tissue from control and CTCE-9908-treated mice were stained with anti-CD34 antibody to determine the effect of CTCE-9908 on tumor angiogenesis." (PMID 24472670, 2014). "The tumor was both CD34-positive and c-kit-positive, which suggested a GIST.He had a medical history of diabetes mellitus and dyslipidemia with severe coronary artery calcification, which was detected by a chest CT scan." (PMID 25022862, 2014). "Compared with the control group, the EIF5A2 knockdown group showed lower micro-vessel density (MVD) as determined by CD34 immunostaining of tumor sample sections." (PMID 25071013, 2014). "The increased presence of these CD34+ cells is induced by tumor-derived granulocyte-macrophage colony-stimulating factor (GM-CSF) and they are chemoattracted into the HNSCC mass by tumor-derived vascular endothelial cell growth factor (VEGF)." (PMID 24202334, 2013). "After processing the data from quantification of endothelial area of interest, we noticed a significant difference of CD34 in tumour (T-REA = 1.95%) versus stroma (S-REA = 0.91%)." (PMID 24073397, 2013). "Frozen tumor sections were immunohistochemically stained with an endothelial specific antibody against CD34." (PMID 23426648, 2013). "Exposure to tumor-derived angiogenic factors promoted the expression of VE-cadherin and vWF, both of which are endothelial-specific markers, in a subset of cultured CD34+ cells (24 ± 8% and 23 ± 10%, respectively)." (PMID 24341512, 2013). "Immunohistochemical studies show strong staining of the tumor cells with CD34, Bcl-2, CD99, and vimentin." (PMID 23662242, 2013). "We have used such a platform to develop a novel technique, namely double-labelling immunostaining of MGMT and a "cocktail" of non-tumour antigens (CD34, CD45 and CD68)." (PMID 24252243, 2013).
tumor (continued). "Immunohistochemically, all tumors expressed CD117, four tumors PDGFRA, ten tumors CD34, eight tumors smooth-muscle actin, one tumor desmin, and S-100 was positive only in the intermixed dendritic cells." (PMID 22350270, 2013). "Immunohistochemistry showed that the tumor cells were diffusely positive for CD34, CD99, Bcl-2 and vimentin." (PMID 24179528, 2013). "High CD34 Chalkley count was found to correlate with larger tumor diameter (P = 0.002), deep invasion (P < 0.001) and HIF-1α (P = 0.04), whereas high VEGF expression correlate significantly with poor tumor differentiation (P = 0.007)." (PMID 24165149, 2013). "The expression of CD34 in the tumor tissues of T (27.60±4.56) group, C (35.80±2.17) and A (15.40±2.07) group was poor, but was high in the G (49.80±4.44) and N groups (48.80±5.81)." (PMID 23833640, 2013). "There was a significant inverse correlation between tumor expression of CD34 and tumor expression of MR (Kramer Phi coefficient: 0.95, Cohen’s kappa: −0.844, p<0.001)." (PMID 23555666, 2013). "The microvessel density and Ad replication in tumor tissue were evaluated by checking the expression of CD34 and hexon proteins, respectively." (PMID 24124726, 2013). "Analysis with Spearman’s rank correlation revealed that LAT1 expression was significantly correlated with Ki-67 and CD34 in all tumor location except CD34 in IHCC (online only)." (PMID 24131658, 2013). "Lungs containing discrete tumor nodes where inflation fixed and taken for haematoxylin and eosin staining as well as CD34 staining for correlation to MRI." (PMID 23382996, 2013). "To test if the p27IRES-VEGF rescue of apoptosis in high dose (20 mg/kg) treated mice correlated with tumor bed angiogenesis, we stained for CD34+ microvessels." (PMID 23533410, 2013). "The main tumour spindle-shaped cells as well as those entrapped within the fat lobules were positive for CD34, BCL2, ER, AR, and CD10 (weak)." (PMID 24459597, 2013). "Immunostaining signal of IL-6, TNFα and VEGF was localized in the cytoplasm of tumor cells and CD34 was localized in endothelial cells of newly formed vessels." (PMID 23688241, 2013). "The results of neo-vascularization confirmed the significantly higher expression of CD34 marker in BT-474 tumors compared to non tumor tissues." (PMID 24278212, 2013). "In another study, treatment with oral Vit D3 in patients with HNSCC reduced the number of immune suppressive CD34+ cells and skewed immune system toward an anti-tumor Th1 immune response." (PMID 23508517, 2013). "High CD34 Chalkley count was found to correlate significantly with larger tumor diameter (P = 0.002) and deeper invasion (P < 0.001), whereas high VEGF expression correlate significantly with poor tumor differentiation (P = 0.007)." (PMID 24165149, 2013). "Immunohistochemical analysis identified a decrease in the number of CD34-positive microvessels of frozen tumor sections in mice treated with SC-560, celecoxib and Taxol." (PMID 23426648, 2013). "In the 2-D microvessel analysis, we examined the same tumor regions to acquire the number of CD34-enclosed areas on the confocal micrographs at 15, 30, and 60 μm under the specimen surface." (PMID 24324559, 2013). "Immunohistochemically, these spindle tumor cells showed diffuse CD34 and Bcl-2 positive reactivity, S-100 protein and HMB45 were negative, Masson colouration disclosed lots of collagenous fiber." (PMID 24294990, 2013). "Whilst all the spindle cells within the tumour expressed CD34, AR, ER, BCL2, and CD10, only those within the myofibroblastoma expressed desmin and only those within the lipomatous areas expressed S100." (PMID 24459597, 2013). "One paper additionally reports that the antiapoptotic factor Bcl-2 is strongly expressed in 90% of tumours with CD34 expression in as much as 78% of cases." (PMID 23634309, 2013).